ENSG00000284906 (novel protein)
Gene: Protein-coding gene on chromosome 15 (30,624,548 to 30,773,002, forward strand). Ensembl gene ENSG00000284906.
Genetic constraint (gnomAD): Loss-of-function variants: 14 observed, 26 expected, observed/expected ratio (o/e) 0.54, 90% interval 0.35 to 0.84. The synonymous counts are far from expectation, so gnomAD's model fits this gene poorly and the ratio says little. Missense variants: 245 observed, 313.75 expected, observed/expected ratio (o/e) 0.78, 90% interval 0.7 to 0.87. Synonymous variants: 82 observed, 110.87 expected, observed/expected ratio (o/e) 0.74, 90% interval 0.62 to 0.89.